INS (insulin)
Diseases named in the same sentence as INS in open-access papers (continued):
Sharing a sentence is not in itself a finding about the gene and the disease.
Obesity (continued). "EVs from individuals with obesity decrease insulin stimulated 2‐deoxyglucose uptake in adipocytes (p = 0.0159)." (PMID 29292863, 2018). "Studies performed in last decades have pointed out the bioactive effects of the flavonoid hesperidin against obesity-related alterations, mainly because to its TG-lowering, anti-inflammatory, antioxidant, and insulin-sensitizing effects." (PMID 30305645, 2018). "Considering the involvement of ANGPTL4 in fat uptake and storage, and its potential role in glucose metabolism, it is of interest to investigate the role of ANGPTL4 in metabolic dysfunction and insulin sensitivity during obesity." (PMID 29502266, 2018). "Transgenic overexpression of vaspin in AT in mice markedly ameliorated glucose and insulin tolerance as well as adipose tissue inflammation under high fat diet-induced obesity." (PMID 28932870, 2018). "This leads to an extreme obesity, but of a metabolically “healthy” phenotype with many small and insulin- sensitive cells." (PMID 29247377, 2018). "Metabolic abnormalities, inappropriate insulin signaling, and activation of inflammatory pathways have been proposed as obesity-mediated mechanisms of oncogenesis." (PMID 30487446, 2018). "This study revealed that impaired leptin and insulin signaling mediated exacerbated obesity and glucose dysregulation through the interaction of the APP/PS1 genotype and HFD." (PMID 30096853, 2018). "According to Hall, the carbohydrate–insulin model of obesity theorizes that diets high in carbohydrate are particularly fattening due to their propensity to elevate insulin secretion." (PMID 29541907, 2018). "Impaired vascular insulin signaling is proposed as an important contributor to the development of macro- and micro- vascular diseases in the patients with obesity or with type II diabetes." (PMID 30416448, 2018). "Obesity promotes disruptions in multiple metabolic pathways, such as up-regulated sex steroid hormones, insulin, inflammatory mediators and lower levels of adiponectin." (PMID 30191141, 2018). "Insulin‐stimulated glucose transport was decreased in cells treated with EVs obtained from women with obesity." (PMID 29292863, 2018). "MCP-1, in concert with other pro-inflammatory cytokines such as TNF-α or IL-6 overexpressed by adipocytes in obesity and MetS, leads to insulin sensitivity." (PMID 29507613, 2018). "Randomized controlled trials among survivors of obesity-related cancers have shown favorable insulin and insulin-like-growth factor (IGF), inflammation, and immune system responses to enhanced exercise." (PMID 29894512, 2018). "Under conditions of obesity and insulin resistance, insulin loses its ability to suppress gluconeogenic mRNAs in liver, yet the hormone continues to stimulate SREBP-1c production and fatty acid synthesis in that organ." (PMID 29952285, 2018). "By contrast, in ten adults with PHP1A, four already had a diagnosis of type 2 diabetes mellitus, the fasting plasma levels of glucose and HbA1c were higher than the controls with obesity, and they showed decreased insulin sensitivity." (PMID 29959430, 2018). "In our studies, IL6 upregulation, seen after BP3 treatment, matches with improved insulin sensitivity, obesity and steatosis in IL6 transgenic mice, likely by suppressing gluconeogenic and lipogenic enzymatic cascade via hepatic STAT3 phosphorylation." (PMID 30374109, 2018). "FGF21 has diverse metabolic effects that are beneficial for managing obesity, increasing fatty acid oxidation in the liver, and improving insulin sensitivity in obese individuals." (PMID 30275865, 2018). "CD1d-deficient HFD-fed mice have decreased ATM recruitment, resulting in reduced obesity and improved insulin sensitivity." (PMID 28661198, 2018). "Resolvins, a novel family derived from EPA and DHA, have anti-inflammatory and insulin sensitizing properties and it has been suggested that they play a role in the amelioration of obesity-related metabolic dysfunctions." (PMID 29538286, 2018).
Obesity (continued). "As expected, obesity was associated with higher plasma levels of TAG, insulin, HOMA-IR, NEFAs, and CETP and lower plasma levels of HDL-C and Apo AI in the total samples." (PMID 30365817, 2018). "In summary, four different approaches to lowering insulin secretion had the same consequence: prevention or remission of obesity." (PMID 30541568, 2018). "Mito-Ob mice develop obesity-related impaired glucose homeostasis and insulin sensitivity in a male-specific manner suggesting a potential involvement of gonadal sex steroid hormones in the observed differences in metabolic phenotype." (PMID 30157935, 2018). "It has been demonstrated that the deletion of TBC1D1 modifies glucose, lipid, and energy homeostasis impacting insulin resistance, body fat metabolism, leading to the development of obesity." (PMID 29882907, 2018). "Mouse models that express the full length HTT gene with around 100 CAG repeats, the YAC128 and BACHD mice, display increased body weight and develop obesity with insulin and leptin resistance." (PMID 29403354, 2018). "Excessive insulin also invokes synchronous increases in levels of Abeta and inflammatory agents, effects that are exacerbated by age and obesity." (PMID 30042911, 2018). "Conversely, the adipokine adiponectin decreases with obesity and metabolic dysfunction, and is generally known to potentiate insulin sensitivity and promote energy homeostasis." (PMID 30400566, 2018). "Continuous deficiency of leucine, a member of branched chain amino acids, is able to reduce obesity and improve insulin sensitivity in mice." (PMID 30294696, 2018). "It will be necessary to design specific studies to try to clarify insulin–amylase–glucagon relations in health and obesity." (PMID 30293998, 2018). "In order to study cardiac function independently of the effect of obesity, hyperinsulinemia and high-glycemic load, we selected animals within each sex group that had similar body weight as well as normal insulin and FBG levels." (PMID 30589871, 2018). "GLP-1R agonists have previously been shown to either prevent or ameliorate experimental obesity and preserve insulin sensitivity in multiple preclinical models." (PMID 30459598, 2018). "MLB supplementation ameliorated aging or obesity-induced disruption of insulin signaling in the liver." (PMID 30134566, 2018). "Confounding effects of obesity also render it difficult to demonstrate an independent effect of CPAP therapy on insulin sensitivity." (PMID 30426019, 2018). "This inflammation in turn contributes to both insulin and leptin resistance, promoting further obesity and subsequently diabetes." (PMID 29743077, 2018). "Subjects with obesity frequently have basal hyperinsulinemia and an exaggerated response to stimulation by a test meal or glucose attributed to increased insulin secretion and reduced insulin clearance." (PMID 29471797, 2018). "The purpose of this study was to examine early alterations in brain insulin signaling, inflammatory/stress markers, and energetic stress in a model of diet‐induced obesity during middle age." (PMID 29890051, 2018). "Insulin is secreted from pancreatic beta cells following an increase in blood glucose; however, insulin levels also become elevated in states of obesity due to insulin resistance of metabolic tissues including muscle and adipose tissue." (PMID 29868016, 2018). "Higher kisspeptin levels in diabetic patients as well as diabetic/obesity mice were observed, while kisspeptin knockdown led to insulin secretion and improved glucose intolerance." (PMID 29593567, 2018). "Adipokines were sorted into four categories–pro-inflammatory, obesity-related, insulin-pathway and FGFs–all of which were increased in transgenic mice compared to WT littermates." (PMID 29652901, 2018). "The db/db mouse is the most popular animal model used by pharmaceutical companies to test blood glucose lowering agents, insulin sensitizers, insulin secretagogues, and anti-obesity agents." (PMID 30666198, 2018).
Obesity (continued). "Pregravid obesity is characterized by insulin and leptin resistance, high levels of circulating inflammatory markers IL-6 and CRP, in addition to chemokine IL-8 (p < 0.01)." (PMID 30131724, 2018). "On the other hand, higher insulin was related to lower frontal, temporal, and insula surface area and volume, regions that were found affected in this study or in other obesity and T2DM studies." (PMID 29654499, 2018). "There were also 35.2% of candidate genes (25/71) related to metabolism, such as circulating glucose and insulin level, obesity, and so on." (PMID 30429843, 2018). "Resistin, a cysteine-rich hormone secreted by rodent fat cells, was found to impair glucose metabolism and insulin action in mouse models of obesity and cultured adipocytes." (PMID 30353146, 2018). "The aim of the present study was to investigate the regulation and function of NECC2 in adipocytes and to establish its relationship to obesity and insulin sensitivity." (PMID 30160359, 2018). "The RQ in both the basal and insulin-stimulated conditions was substantially lower in women with PCOS compared to the women with normal BMI or obesity." (PMID 30377436, 2018). "Some of the consequences of overnutrition-induced obesity are hyperinsulinemia and hyperleptinemia, resulting in insulin and leptin resistance respectively." (PMID 30202241, 2018). "Obesity with excessive accumulation of visceral fat around and within the abdominal organs and increased flow of fatty acids to the liver disrupts insulin secretion, increasing insulin resistance and production of glucose in the liver." (PMID 30894898, 2018). "For instance, diet-induced obese mice with PGRN deficiency exhibited lower body weight and ameliorated insulin sensitivity, whereas administration of recombinant PGRN induced obesity and glucose intolerance in wild-type mice with standard diet." (PMID 30151059, 2018). "Oral GABA administration inhibited obesity, reduced fasting blood glucose, and improved glucose tolerance and insulin sensitivity in high-fat diet-fed C57BL/6 mice." (PMID 29867762, 2018). "Tissue inflammation is a general feature of obesity and appears to play a role in the brain insulin resistance created by the changing gut microbiota." (PMID 29910467, 2018). "Obesity impedes the regulation of glucose control by disturbing insulin signaling transduction, which has been shown to be affected by the gut microbiome." (PMID 29636788, 2018). "In obesity, treatments targeting the reduction of blood glucose, or increasing insulin sensitivity can be carried out while monitoring ghrelin levels." (PMID 30298019, 2018). "Meanwhile, adiponectin is a 30 k Da adipokine that is produced in adipose tissues and its levels inversely correlate with obesity to regulate glucose and lipid metabolism, as well as insulin sensitivity." (PMID 29558403, 2018). "Obesity is responsible for suppression of insulin signalling by hyperactivation of c-jun N-terminal kinase (JNK) through increased ER stress." (PMID 29925420, 2018). "Mice with a knock-out of the AR suffer a late onset of obesity while being normally sensitive to insulin." (PMID 30231878, 2018). "How DPP-4 inhibitor attenuates the activation of the S6K1 in the setting of overnutrition- and obesity-induced INS resistance as well as its relation to β-cell function is yet fully elucidated." (PMID 30116740, 2018). "As such, understanding and reversing defects in vascular insulin signaling contributes to prevention of cardiovascular complications of obesity and DM2." (PMID 29628894, 2018). "Taken together, our work provides evidence that elevated endogenous FGF21 in obesity serves as a defense mechanism against systemic insulin resistance." (PMID 29348470, 2018). "The aim of the study is to offer new insights in PCOS patients strictly selected in order to avoid confounding factors such as dyslipemia, obesity, altered glucose/insulin metabolism, cardiovascular disease, or cancer." (PMID 29435121, 2018).
Obesity (continued). "During the OGTT, the glucose tolerance and insulin secretion in CS and SS offspring were comparable to CC offspring despite obesity, suggesting a compensatory response compared to the findings at 12 weeks of age." (PMID 30026488, 2018). "As a result, regular physical activities and exercise were reported as the most effective methods for preventing and treating NAFLD, as they lower obesity, enhance insulin sensitivity, and improve blood glucose metabolism." (PMID 30661332, 2018). "While they developed obesity in a sex-neutral manner, the progression of obesity-related impaired glucose homeostasis and insulin sensitivity was male-specific." (PMID 30157935, 2018). "A study with mice demonstrated that maternal consumption of a high-fat diet supplemented with resveratrol during pregnancy and lactation was able to improve insulin sensitivity and reduce obesity in the offspring receiving the high-fat diet." (PMID 30020947, 2018). "Adiponectin has been demonstrated to exhibit insulin sensitizing and anti-inflammatory properties, and serum levels of adiponectin are negatively correlated with obesity." (PMID 29587377, 2018). "Studies in humans and animal models show that cardiac insulin signalling is preserved or increased in diet-induced obesity, T2D, and heart failure." (PMID 30443826, 2018). "Genetic deletion of PTP1B in mice results in insulin sensitivity and protects mice against high-fat diet-induced obesity." (PMID 29396779, 2018). "Collectively, these results suggest that adipocyte AMPK play a vital role in combating HFD-induced obesity, dysregulated glucose homeostasis and insulin resistance." (PMID 29515462, 2018). "In prepubertal girls with obesity, both insulin sensitivity and intra-abdominal adipose tissue remained unchanged following a strength-training program." (PMID 29471797, 2018). "Specifically, in obesity, adipose tissue is resistant to the effects of insulin to inhibit lipolysis and promote additional energy storage as well as being resistant to the effect of catecholamines to stimulate lipolysis." (PMID 29661693, 2018). "Female mice were reported to be significantly less sensitive than male mice to high fat diet-induced obesity, insulin resistance, systemic inflammation and learning deficits." (PMID 30070999, 2018). "Defects in mitochondrial biogenesis lead to the excess of reactive oxygen and the subsequent reduction in energy expenditure, which are the main disruptors of insulin signaling in obesity." (PMID 30572687, 2018). "Despite the delayed absorption, the regional differences in insulin absorption rate appear to be maintained with obesity." (PMID 30116732, 2018). "Accordingly, we cannot exclude that other metabolic changes, such as obesity, increased insulin levels, or impaired insulin signaling, contribute to a “memory” effect in type 2 diabetic patients." (PMID 30271984, 2018). "Of the new loci identified, EPAC1 (RAPGEF3) is known to play a role in energy homeostasis, diabetes and obesity propensity and regulates insulin and leptin signalling." (PMID 30121879, 2018). "An increasing tendency of their variable levels was observed, except on HOMA2-IR, HOMA2-βcell, HOMA2-S, insulin and glucose levels whose values were higher in sick subjects; while individuals with obesity had lower levels of HDL-C." (PMID 35136588, 2018). "In rats, L-arginine supplementation decreased fat mass and insulin levels in both genetic and dietary obesity models." (PMID 29209827, 2018). "Inhibition of the ER localized enzyme increases insulin sensitivity and resistance to diet-induced obesity." (PMID 30547786, 2018). "Mechanistically, obesity—a state of excess nutrient levels—chronically activates signaling pathways that upregulate insulin, insulin-like growth factor (IGF), leptin, and inflammatory cytokines (e.g., IL-6) and increases the risk of neoplastic transformation." (PMID 30208162, 2018).
Obesity (continued). "It is well established that obesity and a sedentary lifestyle, typical of DM2 patients, result in a loss of insulin sensitivity, with greater insulin needs at mealtimes." (PMID 30918874, 2018). "FGF21 treatment of mice was shown to correct obesity and to improve insulin sensitivity and glucose control in rodents and humans." (PMID 30547786, 2018). "Leptin is well characterized in metabolism and metabolic syndrome, and hyper-leptinemia and leptin resistance due to obesity can have detrimental effects on the β-cell, contributing to impaired glucose stimulated insulin secretion and proliferative capacity." (PMID 30400566, 2018). "(b) These results emphasize the roles of AbdAT miRNAs (i.e., miR-24, miR-30d, and miR-146a) and SFRP4 in regulating mechanisms that govern AbdAT remodeling and systemic insulin sensitivity in obesity and T2DM." (PMID 29721017, 2018). "These inflammations increase the expression of TNF-α and NF-κB, and affect the secretion of metabolic hormones, such as insulin, adiponectin, leptin, and resistin, promoting obesity." (PMID 29707542, 2018). "In mice with high fat diet (HFD)-induced obesity, JBSNF-000088 treatment caused a reduction in body weight, improved insulin sensitivity and normalized glucose tolerance to the level of lean control mice." (PMID 29483571, 2018). "Obesity-related cardio-metabolic risks are characterized by hyperinsulinemia (i.e. basal plasma insulin levels >7–10 μU/mL), hypertriglyceridemia, elevated biomarkers of inflammation, and high blood pressure." (PMID 30026913, 2018). "On the contrary, IP6K1 knockout mice manifest insulin sensitivity and are resistant to obesity elicited by high-fat diet or aging." (PMID 30595691, 2018). "Our study is the first study suggesting that exacerbated HFD-induced obesity and glycemic dysregulation in APP/PS1 transgenic mice are associated with impaired insulin and hypothalamic leptin signaling." (PMID 30096853, 2018). "IR is defined as a decrease in the metabolic response of the skeletal muscle cell to insulin, which is a protruding feature of obesity and T2DM." (PMID 30249008, 2018). "WTAP reduction can lead to amelioration of HFD-induced obesity in vivo with suppression of the size and number of adipocytes, resulting in better insulin sensitivity than that of WT mice." (PMID 29866655, 2018). "Under insulin resistant states, such as obesity and T2D, Glut-4 expression is down-regulated specifically in adipose tissue but not in skeletal muscle." (PMID 29534036, 2018). "In fact, in the insulin resistant state of obesity, we found lower levels of citrate and G6P, and the NADH/NAD+ ratio was not affected by BMI." (PMID 30183740, 2018). "This study used a diet-induced obesity (DIO) model to determine the effects of chronic intrahippocampal insulin administration on hippocampal-dependent cognitive impairments in HFD fed C57BL/6J mice in the Morris Water Maze and Y-maze." (PMID 30619085, 2018). "The possible mechanisms through which obesity induces IR are increased fatty acid metabolites, oxidative stress, and inflammation, leading to suppression of the insulin signaling pathways." (PMID 30249008, 2018). "In fact, experimental evidence of SIRT1 overexpression suggests that a decrease in serum insulin and cholesterol occurs in addition to that of adipose tissue volume and obesity-induced insulin resistance." (PMID 30367115, 2018). "Compared with Obesity group, the glucose-lowering effects of insulin were corrected in the EA group based on both IPIT and IPGT." (PMID 30425749, 2018). "Apelin is considered as an anti-obesity peptide which increases the sensitivity of various tissues especially skeletal muscles to insulin, enhances energy consumption, and reduces body fat mass." (PMID 30140406, 2018). "Ideally, in the absence of clinically manifest angiopathy it should be possible to better determine the effects of obesity, blood pressure, and disturbances in glucose and insulin metabolism/production on the brain." (PMID 29654499, 2018).